PMS1 (PMS1 homolog 1, mismatch repair system component)
Description:
Probably involved in the repair of mismatches in DNA.
Synonyms: PMSL1; MLH2; HNPCC3; hPMS1
Tractability: PROTAC: ubiquitination databases record sites on it.
Gene: Protein-coding gene on chromosome 2 (189,784,085 to 189,878,385, forward strand). Ensembl gene ENSG00000064933.
Subcellular location: Nucleus
Subcellular location (Human Protein Atlas): Nuclear bodies; Nucleoplasm
Gene Ontology:
Molecular function: enzyme binding; protein binding; ATP hydrolysis activity; DNA binding; ATP binding; ATP-dependent DNA damage sensor activity; mismatched DNA binding
Biological process: mismatch repair; response to xenobiotic stimulus
Cellular component: MutLbeta complex; nucleus; mismatch repair complex
Genetic constraint (gnomAD): Loss-of-function variants: 45 observed, 53.17 expected, observed/expected ratio (o/e) 0.85, 90% interval 0.67 to 1.09. The upper end of that interval is the gene's LOEUF score, 1.09, which puts it in group 4 of 6, group 1 being the genes least tolerant of losing a copy. Missense variants: 660 observed, 718.15 expected, observed/expected ratio (o/e) 0.92, 90% interval 0.86 to 0.98. Synonymous variants: 218 observed, 245.44 expected, observed/expected ratio (o/e) 0.89, 90% interval 0.79 to 0.99.
Gene-disease validity (ClinGen):
ClinGen rates the evidence that PMS1 causes each of these diseases.
Lynch syndrome (autosomal dominant): Refuted. An autosomal dominant hereditary neoplastic syndrome characterized by the development of colorectal carcinoma and a high risk of developing endometrial carcinoma, gastric carcinoma, ovarian carcinoma, renal pelvis carcinoma, and small intestinal carcinoma.
Homologues: Orthologues: chimpanzee PMS1 (99% identical), macaque PMS1 (97% identical), dog PMS1 (84% identical), pig PMS1 (83% identical), guinea pig PMS1 (82% identical), rabbit PMS1 (79% identical), mouse Pms1 (74% identical), rat Pms1 (72% identical), tropical clawed frog pms1 (47% identical), zebrafish pms1 (45% identical). Paralogues in human: MLH3 (19% identical), PMS2 (18% identical), MLH1 (14% identical).
Diseases named in the same sentence as PMS1 in open-access papers:
PMS1 is named in the same sentence as 63 diseases in open-access papers, as found by Europe PMC text mining. Sharing a sentence is not in itself a finding about the gene and the disease. The quoted sentences say what the papers report.
Lynch syndrome (22 papers, 2009 to 2024). "Both MLH3 and PMS1 genes are suspected to play a role in Lynch syndrome, but the clinical significance of variants in these genes is less clear." (PMID 37656691, 2023). "Variants have also been found together with other MMR gene variants, suggesting PMS1 and MLH3 to be low risk genes in Lynch syndrome." (PMID 27696107, 2017). "MLH (PMS1) and MSH (MSH1 - 6) gene function is significantly correlated with colon cancer; mutations in these genes could cause predisposition and susceptibility to Lynch syndrome, in conjunction with colon cancer." (PMID 34521988, 2021). "MLH3 gene encodes a protein that functions as a heterodimer with other MMR genes, and PMS1 gene encodes a protein that forms a heterodimer with MLH1 and PMS2, products of MMR genes involved in Lynch syndrome (nonpolyposis colorectal cancer, HNPCC)." (PMID 37656691, 2023).
breast carcinoma (14 papers, 1999 to 2025). "Mainly, exploration of the impact of MLH3 and PMS1 germline variants in breast cancer would require further segregation analysis and screening tests such as MSI test in larger breast cancer cohorts." (PMID 37656691, 2023). "In addition, unique germline variants in PMS1 gene have been found in patients with breast cancer and in patients with breast/ovarian syndrome." (PMID 37656691, 2023). "The PMS1 variant (p.Lys455Glu, SCV005329257) was found in a woman who had colon and rectal cancer aged 70 (MSI-H) and had 4 other affected family members: 3 deceased women with breast cancer (35–50 years old) while her surviving brother had prostate cancer (72 years)." (PMID 40823072, 2025). "However, low-risk genes such as MLH3 and PMS1 are not available in the management guidelines, where variants in low-penetrance genes are very rare and correlate with < 2-fold risk of developing breast cancer." (PMID 37656691, 2023). "We carried out a hospital-based case-control study in a Caucasian Portuguese population (287 cases and 547 controls) to estimate the susceptibility to non-familial breast cancer associated with some polymorphisms in mismatch repair genes (MSH3, MSH4, MSH6, MLH1, MLH3, PMS1 and MUTYH)." (PMID 19781088, 2009).
colorectal cancer (14 papers, 2002 to 2025). A primary or metastatic malignant neoplasm that affects the colon or rectum. "Loss of function of PMS1 leads to microsatellite instability and colorectal cancer." (PMID 36281462, 2022). "Since PMS1, MLH3 and EXO1 have only been implicated in the development of colorectal cancers in case reports, they are unlikely to be implicated in the development of cancer in our group." (PMID 16106253, 2005). "A nonsynonymous single-nucleotide variation in PMS1 (rs142159998) gene was detected and assessed as potentially related to the phenotype and led to the recommendation to continue the appropriate Hereditary nonpolyposis colorectal cancer (HNPCC) surveillance." (PMID 26436109, 2015).
ovarian carcinoma (10 papers, 2010 to 2025). A malignant neoplasm originating from the surface ovarian epithelium. "PMS1 mutations or loss of function are associated with various cancers, such as colorectal, gastric, and ovarian cancers." (PMID 39865406, 2025). "In family A, the proband (III: 2) was diagnosed with ovarian cancer at the age of 64 and was found to be a carrier of a novel frameshift pathogenic variant NM_000534.5:c.2294_2295 del in the PMS1 gene (reference sequence NM_000534.5)." (PMID 39436407, 2024). "Also, an ovarian cancer-affected patient identified with a pathogenic variant in the PMS1 gene, is predicted to be disease causing." (PMID 39436407, 2024). "Then, we focused on genes traditionally associated with breast/ovarian cancer or other malignancies, and identified 23 missenses, 2 splicing, and 2 UTR variants mainly affecting genes involved in DNA repair, such as RAD51, RAD54B, PMS1, FANCD2, XRCC1, and BLM." (PMID 35893033, 2022). "Additionally, the lack of cosegregation between the PMS1 pathogenic variants in the patient’s aunt suggests that the PMS1 gene is unlikely to contribute to hereditary ovarian cancer predisposition." (PMID 39436407, 2024).
Hypertension (4 papers, 2009 to 2014). The presence of chronic increased pressure in the systemic arterial system. "Of the 14 major genes, only PMS1, which is responsible for ATP and DNA bindings and is involved in repair of DNA mismatches, has been reported to associate with hypertension in African Americans." (PMID 23879630, 2013). "In contrast to the hypertension results, the T allele of the rs5743185 SNP, an intronic SNP in the PMS1 (GeneID 5378) gene, was strongly associated with SBP (nominal p = 2.09×10−11, Bonferroni-corrected p = 1.69×10−5) among normotensive individuals." (PMID 19609347, 2009). "Besides, the PMS1 gene was also associated with systolic blood pressure and hypertension in a GWAS of 29,136 participants from six large prospective observational studies in the CHARGE Consortium." (PMID 25162662, 2014). "Finally, genes and/or susceptibility loci on the long arm of chromosome 2 have been recently linked to blood pressure and hypertension by genome-wide association studies, such as STK39 at 2q24.3; PMS1 and MSTN, both at 2q32.2; DS2S2382 and DS2S338 at 2q35–q37." (PMID 22686481, 2012). "One of these studies also reported finding significant hits in the CACNB2 gene for hypertension and DBP, a gene with a high-scoring variant for hypertension in the present study and in the PMS1 gene for hypertension and SBP, which scored highly for SBP in this study." (PMID 19609347, 2009).
lung carcinoma (4 papers, 2014 to 2023). "It has been proved that polymorphisms of DNA repair genes, such as the polymorphisms of XPA ‐4G>A (rs1800975), ERCC2 862G>A (rs1799793) 12, MSH3 3133G>A (rs26279), and PMS1 639G>A (rs5742938) 13, are associated with the risk of lung cancer." (PMID 27335251, 2016). "In this study, we evaluated whether polymorphisms in DNA damage and repair genes (EXO1, RPA1, PMS1, and PMS2) were associated with prognosis and response to platinum-based chemotherapy in lung cancer patients." (PMID 36277983, 2022).
rectal cancer (4 papers, 2020 to 2025). A primary or metastatic malignant neoplasm that affects the rectum. "We have previously reported that the rs202195689 SNP in the microRNA seed region and rs5743030, rs4920657, and rs5743100 SNPs in PMS1 are associated with OS in patients with rectal cancer, indicating that these variants may predict the prognosis of patients receiving postoperative CRT26,27." (PMID 37144561, 2023).
endometrial cancer (3 papers, 2019 to 2025). Primary or metastatic malignant neoplasm involving the endometrium (mucous membrane that lines the endometrial cavity).
glioma (3 papers, 2020 to 2025). A benign or malignant brain and spinal cord tumor that arises from glial cells (astrocytes, oligodendrocytes, ependymal cells). "Among these, EID3, MGMT, PMS1, and NUDT1 were significantly related to the prognosis and survival of glioma patients, and the high-risk score group had a significantly shorter survival time." (PMID 37086071, 2023).
Huntington disease (3 papers, 2022 to 2025). Huntington disease (HD) is a rare neurodegenerative disorder of the central nervous system characterized by unwanted choreatic movements, behavioral and psychiatric disturbances and dementia. "Re-analysis of Huntington’s disease AOO exome sequencing data showed that, in the early onset Huntington’s disease group, deleterious variants were enriched in FAN1 and depleted in LIG1, MSH3 and PMS1." (PMID 39801710, 2025).
Familial adenomatous polyposis (2 papers, 2019 to 2025). Familial adenomatous polyposis (FAP) is characterized by the development of hundreds to thousands of adenomas in the rectum and colon during the second decade of life.
oesophageal cancer (2 papers, 2012 to 2020).
aplastic anemia (1 paper, 2014). Anemia resulting from bone marrow failure (aplastic or hypoplastic bone marrow). "In a study of Japanese children with aplastic anemia (AA), IgG antibodies against PMS1 were detected in 10% patients (3/30), while no antibody responses to PMS1 in normal volunteers." (PMID 25162662, 2014).
bladder cancer (1 paper, 2012). "Individuals with the variant forms of DNA repair genes postmeiotic segregation increased 1 (PMS1) and nibrin (NBS1) had a 4-fold higher risk of bladder cancer (OR 4.15 95%CI 1.79–9.66) compared to those wildtype for these SNPs." (PMID 23284679, 2012).
bowel cancer (1 paper, 2021). "In this case-control study, mutations in 8 genes (APC, ATM, MLH1, FANCD2, MSH3, MSH6, PMS1, and RAD51D) were found to be associated with bowel cancer and were present in 3.5% of patients with bowel cancer." (PMID 35154239, 2021).
cardiomyopathy (1 paper, 2013). A disease of the heart muscle or myocardium proper. "From these tables, we found that gene clusters anchored by the major genes CGREF1, PMS1 and TNIK all had multiple genes in several cardiomyopathy-related pathways." (PMID 23879630, 2013).
cervical cancer (1 paper, 2016). A primary or metastatic malignant neoplasm involving the cervix. "PMS1, RAD54B, FAAP20 and BRCA1 exhibited almost uniform hyper- or hypomethylation in the cervical cancer samples." (PMID 27683114, 2016).
hepatocellular carcinoma (1 paper, 2020). A malignant tumor that arises from hepatocytes. "Here we report a case of hepatocellular carcinoma (HCC) with a novel potential pathogenic germline PMS1 mutation." (PMID 32000458, 2020).
hereditary cancer (1 paper, 2024). Malignant neoplasms occurring in families at a rate greater than that expected by chance and caused by germline mutations in a specific gene. "The PMS1 gene’s association with cancer, however, was contradicted in the assessment of gene panels designed for hereditary cancers." (PMID 39436407, 2024). "Additionally, recent studies on hereditary cancers still included the PMS1 gene in their panels." (PMID 39436407, 2024).
mismatch repair deficiency (1 paper, 2016).
non-small cell lung carcinoma (1 paper, 2014). A group of at least three distinct histological types of lung cancer, including non-small cell squamous cell carcinoma, adenocarcinoma, and large cell carcinoma. "As one of the potentially functional polymorphisms in PMS1, the rs5742933 may serve as candidate prognostic marker of clinical outcome of non-small-cell lung cancer." (PMID 25162662, 2014).
papillary thyroid cancer (1 paper, 2018). "In papillary thyroid cancer, oxidative stress causes heavy DNA damage and the downregulation of MMR-associated genes (including MLH3 and PMS1)." (PMID 30451877, 2018).
rectal adenocarcinoma (1 paper, 2023).
sarcoma (1 paper, 2021). A usually aggressive malignant neoplasm of the soft tissue or bone. "PARP3 and PMS1, which were genes associated with a better PFS of trabectedin, were overexpressed in L‐sarcomas and in tumors with a somatic location, whereas PARP1, a gene that correlated with worse PFS of trabectedin, was highly expressed in non‐L‐sarcomas and tumors with visceral location." (PMID 33983674, 2021).
thyroid tumor (1 paper, 2021). A benign or malignant neoplasm affecting the thyroid gland.